SET (SET nuclear proto-oncogene)
Diseases named in the same sentence as SET in open-access papers (continued):
Sharing a sentence is not in itself a finding about the gene and the disease.
Alzheimer disease (11 papers, 2014 to 2024). A progressive, neurodegenerative disease characterized by loss of function and death of nerve cells in several areas of the brain leading to loss of cognitive function such as memory and language. "Since then, accumulating evidence have linked overexpression of SET, aberrant SET splicing, and cellular localization to cancer progression and development of neurodegenerative tauopathies such as Alzheimer’s disease." (PMID 36345878, 2022). "Interestingly, increase of SET expression in brains of patients with Alzheimer’s disease has been associated with the accumulation of phosphorylated Tau in neurons through inhibition of PP2A activity by SET." (PMID 30052687, 2018). "This phosphorylation is mediated by the phosphoinositide-3-kinase γ (PI3Kγ) and Casein kinase 2 (CK2) and it has been correlated to aberrant cytosolic retention of SET in Alzheimer’s disease, in myeloproliferative neoplasms (MPNs) and AML." (PMID 36345878, 2022). "ZFX regulates the expression of SET nuclear proto-oncogene (SET), also known as protein phosphatase 2A inhibitor (I2PP2A), a gene associated with tau protein hyperphosphorylation in Alzheimer’s disease." (PMID 34281203, 2021). "Several studies in Alzheimer’s disease show that CK2 phosphorylates SET on Ser9, in the nuclear localization signal, which is key for SET cytoplasmic localization and inhibition of PP2A, leading to tau hyperphosphorylation." (PMID 31913266, 2020). "The overexpression of endogenous protein inhibitors of PP2A, SET and CIP2A, is tightly linked to the progression of various human cancers, as well as Alzheimer’s disease." (PMID 30341686, 2018). "Taken together, SET dysregulation, most significantly, its overexpression, has been observed in cells/tissues involved in Alzheimer’s disease, PCOS, and cancers." (PMID 27775603, 2016). "We review the molecular mechanisms linking SET dysregulation to tumorigenesis and discuss how SET commits neurons to progressive cell death in Alzheimer’s disease, highlighting the rationale of exploiting SET as a therapeutic target for cancer and neurodegenerative tauopathies." (PMID 36345878, 2022). "Indeed, overexpression of SET has been found in numerous human cancers and in brains of patients with Alzheimer’s disease." (PMID 30052687, 2018). "SET overexpression has been detected in brain neurons of patients suffering Alzheimer’s disease, follicle theca cells of Polycystic Ovary Syndrome (PCOS) patients, and ovarian cancer cells, indicating that SET may play a pathological role for these disorders." (PMID 27775603, 2016). "In addition, other mechanisms including phosphorylation of SET on Serine 24 and 93 and sumoylation at Lysine 68 have also been described as critical sites to target SET in the cytosol; however, these modifications have only been described in models of Alzheimer’s disease." (PMID 36345878, 2022).
colorectal cancer (10 papers, 2014 to 2024). A primary or metastatic malignant neoplasm that affects the colon or rectum. "High SET expression has been implicated in poor survival outcomes in a diverse set of cancers, including colorectal cancer, breast cancer and hepatocellular carcinoma." (PMID 35118387, 2022). "We hypothesize that SET is a diagnostic marker for prognosis, particularly, neoplasm invasiveness in colorectal cancer." (PMID 24944693, 2014). "Overexpression of SET in specimens of colorectal cancer obtained from patients indicated that PP2A inactivation is a common event and deregulation of SET would be a key contributing mechanism to PP2A inactivation." (PMID 37097392, 2023). "GD562 exhibited improved inhibition of the cellular N-terminal methylation levels of both the regulator of chromosome condensation 1 and the oncoprotein SET with an IC50 value of ~50 μM in human colorectal cancer HCT116 cells." (PMID 35209173, 2022). "In colorectal cancer, it was indicated that anchorage-independent cell growth is enhanced by the overexpression of SET." (PMID 33435156, 2021). "Interestingly, our findings demonstrate that miR-199b enhances the sensitivity of colorectal cancer cells to 5-FU in a SET-dependent manner, and that both miR-199b overexpression and SET inhibition are able to overcome resistance to this drug using an acquired 5-FU-resistant model." (PMID 32580513, 2020). "A SET antagonist, FTY720, induced PP2A activity in two human colorectal cancer cell lines, RKO and LoVo, and was inhibited by okadaic acid." (PMID 37097392, 2023). "FTY720-mediated inhibition of SET has shown promising anti-tumor effects through the activation of PP2A in lung cancer, colorectal cancer and various hematologic malignancies." (PMID 35118387, 2022).
chronic myeloid leukemia (9 papers, 2006 to 2021). "Indeed, the importance of the SET/PP2A interplay in cancer has been recently investigated in chronic myelogenous leukaemia in which a SET-mediated inhibition of PP2A phosphatase activity is distinctively occurring in patients with blast crisis CML." (PMID 16953242, 2006). "CIP2A and SET are endogenous inhibitors of the phosphatase 2A (PP2A), a tumor suppressor protein that is recurrently inactivated in acute and chronic myeloid leukemias." (PMID 32110991, 2020). "Additionally, we discovered that the apoE-mimetic peptide OP449 (formerly COG449, Oncotide Inc) inhibits SET, resulting in restoration of PP2A tumor suppressor activity in chronic myelogenous leukemia (CML) and acute myelogenous leukemia (AML)." (PMID 27705940, 2016).
myeloid leukemia (9 papers, 2007 to 2024). A clonal proliferation of myeloid cells and their precursors in the bone marrow, peripheral blood, and spleen. "Our laboratory previously established the association and reciprocal regulation of Rac1 and SET/I2PP2A (inhibitor 2 of protein phosphatase 2A), a nuclear proto-oncogene which, as a protein-fusion with Nup214, is associated with myeloid leukemia." (PMID 23874639, 2013). "The SET protein, also named I2PP2A (Inhibitor 2 of PP2A), TAF-1β or PHAP1, is a potent endogenous inhibitor of PP2A with an important role in myeloid leukemias." (PMID 27092295, 2016).
colon carcinoma (8 papers, 2014 to 2024). "Gene Expression database of Normal and Tumor tissues (GENT2) database analysis also indicated that the expression levels of SET/TAF-Iβ in colon cancer tissues were greater than those in normal colon tissues." (PMID 37746636, 2023). "We show that one of the important epigenetic markers, H2AK119ub is regulated by SET/TAF-Iβ-MIB1 ubiquitinating complex in various cancers including colon cancer in PRC1-independent mechanism." (PMID 37746636, 2023). "We examined the expression patterns of SET/TAF-Iβ in colon cancer tissues by analyzing the publicly available datasets from several databases." (PMID 37746636, 2023). "MiR-199b was commonly downregulated in colon cancer, while the miR target SET nuclear proto-oncogene (SET) was highly expressed and correlated to 5-FU resistance in advanced rectal cancer (LARC)." (PMID 34503164, 2021). "We found that SET (isoforms 1 and 2) expression is upregulated in colon cancer cells compared with immortalized colon epithelial cells." (PMID 31097686, 2019). "The expression of SET has been found in tumor tissues of different human malignant diseases, such as leukemia, Wilms' tumor, aveolar soft part sarcoma, cancer of colon, breast, and NSCLC." (PMID 26575017, 2016). "A small interfering RNA targeting SET was transfected into the human colon carcinoma cell lines, LS174T and SW480." (PMID 24944693, 2014). "In this report, we found that overexpression of SET/TAF-Iβ induces H2AK119ub in colon cancer cells." (PMID 37746636, 2023). "Interestingly, ectopic expression of SET also promoted resistance to chemotherapeutics in colon cancer, nonsmall cell lung carcinoma, and hematologic malignancies." (PMID 31097686, 2019). "Similar results were obtained with colon cancer RKO cells (relatively high expression of SET)." (PMID 31097686, 2019). "Together, our study reveals a novel PRC1-independent epigenetic regulatory mechanism for H2AK119ub by SET/TAF-Iβ and MIB1 in colon cancer." (PMID 37746636, 2023). "In human colon cancers (based on The Cancer Genome Atlas (TCGA) data), the expression of endogenous PP2A inhibitors, CIP2A and SET, correlated positively with the infiltration of CD8+ T cells and CD20+ B cells and negatively with FOXP3+ Treg cells." (PMID 34911954, 2021). "Overexpression of SET in three different colon cancer cell lines, SW480, HT-29 and LS513, resulted in increasing resistance to oxaliplatin and 5-FU, and silencing SET via siRNA oppositely enhanced their sensitivity to this chemoregimen." (PMID 26575017, 2016). "All together, these findings suggest that SET/TAF-Iβ and MIB1 might provide novel mechanism for identifying therapeutic targets for colon cancer." (PMID 37746636, 2023). "Given that SET/TAF-Iβ is upregulated in colon cancer and induces H2AK119ub in HCT116 cells, we next attempted to identify its binding partners that might, along with SET/TAF-Iβ, be responsible for the regulation of H2AK119ub levels." (PMID 37746636, 2023). "Taken together, our data suggest that MIB1 acts as a novel binding partner of SET/TAF-Iβ to form ubiquitination complex and the complex has roles in regulating gene expressions at the transcriptional level through histone modification in colon cancer." (PMID 37746636, 2023).
acute lymphoblastic leukemia (7 papers, 2009 to 2024). Leukemia with an acute onset, characterized by the presence of lymphoblasts in the bone marrow and the peripheral blood. "In the 2022 international consensus classification of acute lymphoblastic leukemia/lymphoma, SET-CAN/NUP214 fusion gene positive has been listed as a subtype of the HOXA gene family in the latest eight temporary entities." (PMID 37909026, 2023).
gastric cancer (7 papers, 2019 to 2024). A primary or metastatic malignant neoplasm involving the stomach. "A study of a gastric cancer cell line revealed that SET expression was positively correlated with cell proliferation and was associated with tumor progression and poor prognosis in human gastric cancer, and it may serve as a potential diagnostic marker." (PMID 32153636, 2020). "Increased SET expression is correlated with poor prognosis in patients with gastric cancer and metastatic colorectal cancer." (PMID 31557212, 2019). "Recently, we found that SET regulates gastric cancer cell stemness by stabilizing transcriptional factor E2F1 protein by suppressing PP2A activity." (PMID 31557212, 2019). "We previously reported that SET is expressed in human gastric epithelial cells although it is much weaker than in gastric cancer cells." (PMID 31557212, 2019). "Immunohistochemistry revealed that SET protein levels in cancer cells were positively correlated with poor prognosis of gastric cancer patients." (PMID 31557212, 2019). "We recently reported that SET protein levels in cancer cells were positively correlated with poor prognosis of gastric cancer patients." (PMID 31557212, 2019). "In gastric cancer (GC), where SET overexpression at both protein and mRNA levels represents a marker of poor prognosis, SET down-regulation by shRNAs impaired GC cell proliferation, colony formation, tumorigenesis, and metastasis in vitro and in vivo." (PMID 36345878, 2022). "The expression of SET is regulated by ZFX, a transcription factor which has a potential role in gastric cancer." (PMID 32190219, 2020).
head and neck squamous cell carcinoma (7 papers, 2015 to 2022). A squamous cell carcinoma that arises from any of the following anatomic sites: lip and oral cavity, nasal cavity, paranasal sinuses, pharynx, larynx, and salivary glands. "We previously demonstrated a connection between SET and hnRNP K function in head and neck squamous cell carcinoma (HNSCC) cells related to splicing processing." (PMID 34058077, 2021). "Overexpression of SET has been demonstrated in head and neck squamous cell carcinoma (HNSCC) and promotes HNSCC cell survival, proliferation and resistance to cell death by cisplatin in vivo." (PMID 33241617, 2021). "SET protein regulated intracellular redox state and sustained autophagy in Head and Neck Squamous Cell Carcinoma (HNSCC) cells, which may play an important role in resistance to the death of HNSCC cells." (PMID 32606327, 2020). "SET protein accumulates in many cancer types, including head and neck squamous cell carcinoma (HNSCC); SET is a member of the INHAT complex that inhibits gene transcription associating with histones and preventing their acetylation." (PMID 28460463, 2017). "Moreover, overexpression of SET fails to induce up-regulation of ATM, BRCA1 and CHK2 and recruitment of BRCA2 to DNA damage foci in head and neck squamous cell carcinoma (HNSCC) lines upon cisplatin treatment, suggesting another important inhibitory role of SET on DNA damage repair." (PMID 36345878, 2022).
lymphoma (6 papers, 2009 to 2025). A malignant (clonal) proliferation of B- lymphocytes or T- lymphocytes which involves the lymph nodes, bone marrow and/or extranodal sites. "Previous work has demonstrated that the SET antagonist FTY720 activates PP2A, is cytotoxic to primary chronic lymphocytic leukemia cells, and decreases lymphoma xenograft tumor growth." (PMID 25945834, 2015).
melanoma (6 papers, 2009 to 2023). A malignant, usually aggressive tumor composed of atypical, neoplastic melanocytes. "We previously reported that SET KD suppresses p70 S6 kinase (p70S6K) phosphorylation, a marker for mTORC1 (mammalian target of rapamycin complex 1) signaling activation, in canine melanoma cells." (PMID 28655918, 2017). "SET (Suver3-9, enhancer of zeste, trithorax), which is overexpressed in melanoma cells, inhibits the EGCG-induced PP2A activation." (PMID 26754091, 2016). "It has been shown that miR-21-5p is upregulated in melanoma, NSCLC, GC and promotes tumor proliferation and invasion by targeting CDKN2C/SET/TAF-Iα." (PMID 37308993, 2023). "Additionally, Suvar3–9, an enhancer-of-zeste trithorax (SET), an oncoprotein that inhibits the activity of PP2A, is overexpressed in melanoma." (PMID 36014370, 2022). "EGCG (5 μM) activates PP2A and inhibits cell growth without affecting SET expression in melanoma." (PMID 36014370, 2022).
non-small cell lung carcinoma (6 papers, 2016 to 2021). A group of at least three distinct histological types of lung cancer, including non-small cell squamous cell carcinoma, adenocarcinoma, and large cell carcinoma. "Previously, SET KD was shown to sensitize A549 human non-small cell lung cancer cells to cisplatin by PP2A-dependent activation of the transcriptional factor NDRG127." (PMID 28655918, 2017).
prostate carcinoma (6 papers, 2011 to 2024). A carcinoma that arises from epithelial cells of the prostate gland. "Since we observed high expression of SET mRNA in metastasis we considered whether SET could be associated with androgen independent prostate cancer progression." (PMID 26563471, 2015). "In summary, our data support a role for SET inhibition as a therapeutic option for treatment of castrate resistant prostate cancer driven by PI3K-Akt activation." (PMID 26563471, 2015). "First, we stained for SET using a protein array with lysates from 25 prostate cancer patients and 15 normal prostate samples spotted in triplicate on the array in 5 dilutions." (PMID 26563471, 2015). "Collectively, these data indicate SET is overexpressed in nearly one half of prostate cancer samples and suggest that increased SET expression correlates with progression to androgen independence and biochemical recurrence." (PMID 26563471, 2015). "Our data is corroborated by analysis of prostate cancer patient cohorts showing significant elevation of SET transcripts." (PMID 26563471, 2015). "We found that SET was frequently overexpressed both at the transcript and protein level in prostate cancer cell lines and primary human cancer samples." (PMID 26563471, 2015). "Gain of function analysis reveals that SET, alone, can induce pathological alterations in normal murine prostate tissue thus supporting a functional role for SET in prostate cancer progression." (PMID 26563471, 2015). "Since PP2A expression is reduced in multiple cancers, we investigated the expression profile of the PP2A inhibitor, SET, in prostate cancer progression." (PMID 26563471, 2015). "To determine if human prostate cancer cells require elevated SET expression during progression, we used lenti virus to introduced SET or control shRNAs to constitutively knock down SET in PC3 cells." (PMID 26563471, 2015). "Inhibition of SET through knock down studies demonstrates that enzalutamide resistant prostate cancer cells are exquisitely sensitive to reduced SET function." (PMID 26563471, 2015). "Fourteen DNA repair genes and 15 hormone-regulated genes contributed to the high trigger score for the 7p14.3 variant, of which DAZAP2, DDX18, SET, and XRCC5 were also significantly deregulated in SPOP mutant as compared to SPOP wild-type human prostate carcinoma cases." (PMID 28663546, 2017). "Quantification of SET expression demonstrated significant elevation in cancer compared to benign tissues (p < 0.0002) - observations that were recapitulated in human prostate cancer cell lines." (PMID 26563471, 2015). "It was reported that the suppression of SMYD3 could attenuated malignant phenotype of prostate cancer either by deleting the SET function domain or silencing SMYD3, indicating the function of SMYD3 on tumor growth might associated with histone methyltransferase activity." (PMID 29029425, 2017). "Together, these observations demonstrate that enhanced SET expression is sufficient to induce pathological alterations in Wt murine prostate epithelium and that SET may collaborate with other genetic events relevant to human prostate cancer." (PMID 26563471, 2015). "We show that targeting the endogenous PP2A regulator, SET (I2PP2A), is a viable strategy to inhibit prostate cancers that are resistant to androgen deprivation therapy." (PMID 26563471, 2015). "With this, we considered the possibility that SET inhibition and the resulting PP2A activation may be a suitable strategy to inhibit growth in castration resistant prostate cancer." (PMID 26563471, 2015).